PER2 (period circadian regulator 2)
Diseases named in the same sentence as PER2 in open-access papers (continued):
Sharing a sentence is not in itself a finding about the gene and the disease.
breast cancer (continued). "The Per2 gene has been shown to act as a tumour suppressor in luminal breast cancers by linking the circadian oscillator system to the ERα function." (PMID 26220712, 2015). "Another study illustrated that 95% of the breast cancer cells tested in women showed aberrant promoter methylation in the Period genes, including Per1- and Per2-promoter hypermethylation." (PMID 26220712, 2015). "Based on this knowledge, we then focused on Per2 as a molecular target for the sensitization of resistant breast cancer cells to Dox treatment." (PMID 26347774, 2015). "Collectively, results obtained for the genetic modulation of Per2 demonstrate that the resistant nature of the MDA-MB-231 breast cancer cells to Dox treatment was effectively abrogated via the disruption of the intrinsic circadian clock system." (PMID 26347774, 2015). "Our results show that Per2 silencing effectively sensitizes the chemoresistant MDA-MB-231 breast cancer cells to the cytotoxic effects of doxorubicin." (PMID 26347774, 2015). "Overexpression of PER2 has been shown to inhibit cell growth and the rise of clonogenic cells in breast cancer cells." (PMID 24789043, 2014). "The key circadian genes, PERIOD 2 (PER2 variant 2), CLOCK, TIMELESS, CRYPTOCHROME 1 (CRY1) and CRYPTOCHROME 2 (CRY2) were all also significantly expressed in all breast cancer cell lines and all patients’ breast cancer tissues examined." (PMID 24683528, 2013). "Promoter hypermethylation concomitant with a decrease in expression was identified for the circadian genes PER1 and PER2 in breast cancer." (PMID 23033966, 2012). "Expression of Per2 in these breast cancer cells results in inhibition of cell growth and induction of apoptosis demonstrating the tumor suppressive nature of PER2." (PMID 20353609, 2010). "It has been demonstrated recently that Per2 is endogenously expressed in human breast epithelial cell lines but is not expressed or is expressed at significantly reduced level in human breast cancer cell lines." (PMID 20353609, 2010). "For example, the Zinc Finger Protein 704 (ZNF704)-SIN3 Transcription Regulator Family Member A (SIN3A) transcriptional repressor complex destabilizes period circadian regulator 2 (PER2) transcription, destabilizing circadian rhythms and driving breast cancer progression." (PMID 40725147, 2025). "As a tumor suppressor, PER2 exerts significant inhibitory effects on breast cancer cells." (PMID 40243466, 2025). "Furthermore, alterations in Per2 have also been related to different types of cancers such as lung cancer, breast cancer, and HNSCC." (PMID 37834478, 2023). "Additionally, in colon and breast cancer mouse models, PER2 in the TME played a critical role in tumor initiation and metastasis." (PMID 37524704, 2023). "In their study, western blotting showed that the expression of PER1 and PER2 decreased in the rhythm group, whereas the expression of breast carcinoma amplified sequence 4 (BCAS4), tubulin beta-2B chain (TUBB2B), and Roof Plate-Specific Spondin-4 (RSPO4) increased in the breast cancer group." (PMID 38074657, 2023). "PER2 is a tumor suppressor and is upregulated in breast cancer." (PMID 35606376, 2022). "Additionally, polymorphisms of rhythm genes, including BMAL1, CRY2, PER1, PER2 and PER3, are associated with susceptibility to breast cancer." (PMID 35180863, 2022). "Indeed, the use of PER2:Luc had been previously used to demonstrate this rhythmic expression of PER2 in low malignancy breast cancer cells, and more recently in cervical and esophageal cancer cell lines." (PMID 33810377, 2021). "Moreover, overexpression of PER2 in MCF-7 leads to significant inhibition of breast cancer cell proliferation." (PMID 31739444, 2019). "Coexpression of Per2 with cytochrome inhibits growth of breast cancer cells." (PMID 29607311, 2018).
breast cancer (continued). "This work was corroborated by showing that complete loss of PER2 mRNA oscillations occurred only in ERα-positive breast cancer cells, while ERα-negative breast cancer cells retained partially rhythmic oscillations." (PMID 29780357, 2018). "Dai and Colleagues suggested that individuals carrying both the CLOCK rs3805151 (not considered in our study) CC and PER2 TT genotype had an increased breast cancer risk (OR 2.28; 95% CI 1.22–4.26)." (PMID 30518396, 2018). "In addition, downregulation of PER2 increases β-catenin in human colon cancer cells and in the breast cancer cell line (MTCL)." (PMID 28220106, 2017). "We recently reported that in spite of their failure to express the tumor suppressor and clock gene Per2, our tissue-isolated human breast cancer xenografts exhibit daily oscillations in the expression of Clock, Cry1 and Bmal1 that were disrupted in the absence of a circadian melatonin signal." (PMID 25099274, 2014). "Since that time, the molecular underpinnings of the impact of chronobiology on breast cancer progression have been investigated with clock proteins, such as PER1 and PER2, having notable dysregulation in advanced cancers." (PMID 38534802, 2024). "They report a similar downregulation of PER1, PER2, CRY2, and HLF, in breast cancer samples while CLOCK, ARNTL(BMAL1), and BHLHE40 levels remained relatively unchanged." (PMID 38319971, 2024). "Studies have shown that EMT in glioma C6 and breast cancer MCF-7 cells correlated with enhanced circadian rhythms and increased PER2 gene expression." (PMID 38813085, 2024). "In fact, the expression of certain specific circadian genes (BMAL1, PER2, and TIMELESS) has been demonstrated to be disrupted in breast cancer cell lines." (PMID 36012374, 2022). "Comparing breast cancer to adjacent tissue, PER1, PER2, PER3, and CRY2 levels are decreased; CLOCK is increased; and CRY1 downregulation was found to escalate directly with breast cancer stage." (PMID 35163264, 2022). "The role of clock proteins (e.g., Per2 and BMAL1) has been recently proposed in DOX-induced cell death and breast cancer." (PMID 31973180, 2020). "Other studies have revealed that PER1, PER2, PER3, and CRY2 expression are downregulated in breast cancer tissues, whereas CLOCK and TIMELESS expression are upregulated." (PMID 33114496, 2020). "Some studies have indicated similar results showing that genes PER1, PER2, PER3, and CRY2 were down-expressed in breast cancer tissues." (PMID 29958276, 2018). "A significantly decreased mRNA level in the breast cancer tissue samples was observed for CRY2 (β-coefficient -0.424, p<0.0001), PER1 (β-coefficient -0.371, p<0.0001), PER2 (β-coefficient -0.149, p = 0.037) and PER3 (β-coefficient -0.231, p = 0.001)." (PMID 29958276, 2018). "In more than 95 % of breast cancer tissue from 55 women, expression levels of PER1, PER2, and PER3 were severely disrupted in comparison with adjacent non-cancerous tissue." (PMID 27492458, 2016). "This study was therefore aimed at characterizing the role of Per2 in normal breast epithelia (MCF-12A) and in ER− breast cancer cells (MDA-MB-231) and also at determining the role of Per2 in doxorubicin-induced cell death." (PMID 26347774, 2015). "The suppression of the 45 kDa Per2 protein by means of a targeted esiRNA approach, in the context of Dox-induced cell death, resulted in cell cycle arrest of the MDA-MB-231 breast cancer cells, with a concomitant increase in apoptosis." (PMID 26347774, 2015). "Overexpression of Per2 in the mouse Lewis lung carcinoma cell line (LLC) and mammary carcinoma cell line (EMT6) results in reduced cellular proliferation and rapid apoptosis, but not in non-tumorigenic NIH3T3 cells." (PMID 20353609, 2010). "Downregulations of PER1, PER2, or PER3 have been observed in various cancers, including oral squamous cell carcinoma, head and neck squamous cell carcinoma, colorectal cancer, breast cancer, ovarian cancer, melanoma, and hematological malignancies." (PMID 38813085, 2024).
breast cancer (continued). "Similarly, E2 induced an increase in PER2 mRNA expression mediated by a conserved ERE present in the PER2 gene promoter in the human embryonic kidney cell line 293T and human breast cancer cell line MCF." (PMID 35763527, 2022). "For instance, PER2 may suppress EMT and tumor malignancy in breast cancer cell lines and in glioma cells." (PMID 34065633, 2021). "Importantly, a chemopreventive regimen of dietary MSC restored circadian expression of clock (i.e., Per2) and DDRR genes towards the levels in mammary glands of resistant COP rats, reducing the incidence of mammary tumors by 63% in NMU-treated F344." (PMID 28427145, 2017). "Additionally, the deregulated expression of the circadian related genes PER1, PER2 and PER3 in breast cancers has been studied." (PMID 25041817, 2014). "Rhythmicity of Bmal1 and Per2 promoters in MDA-MB-231 breast cancer cells after serum synchronization could not be observed." (PMID 38199564, 2024). "It has also been suggested that PER2 is downregulated in HCC, chronic myeloid leukemia, pancreatic cancer, and CRC, HNSCC, and breast cancer but not in endometrial cancer." (PMID 33114496, 2020). "Our previous studies have revealed down-regulation of PER2 in HCC, CML, HNSCC, and breast cancer but not in endometrial cancer." (PMID 24708606, 2014). "We found that AITC did not affect PER2 expression, suggesting AITC may not modulate this molecule in MDA-MB-231 breast cancer cells." (PMID 29300316, 2018).
glioma (44 papers, 2012 to 2025). A benign or malignant brain and spinal cord tumor that arises from glial cells (astrocytes, oligodendrocytes, ependymal cells). "The lower level of Per2 expression was found to be linked with high-grade gliomas and elevated expressions of epidermal growth factor receptors as well as proliferating cell nuclear antigens." (PMID 40495887, 2025). "The present results revealed a novel mechanism of action of PER2, underlying the role of PER2 in lipid metabolism, as well as a new drug to prevent glioma progression." (PMID 37069338, 2023). "When Per2 overexpression was induced in glioma cells with Id3 overexpression, Per2 alleviated the increased malignancy of glioma caused by Id3, as shown by multiple experiments." (PMID 35599595, 2022). "We analyzed TCGA and CGGA databases for seeking association among Per2, Id3, and clinical features in glioma." (PMID 35599595, 2022). "High Per1 and Per2 expression were associated with increased sensitivity to irradiation in glioma tissue." (PMID 36066207, 2022). "In this study, Per2 and Id3 were expressed in glioma tissues and were shown to be associated with patient outcomes in glioma patients." (PMID 35599595, 2022). "In the same line, PER2 was found to be downregulated in samples from the TCGA database, and deregulation in PER2 tumor expression was associated with higher mortality in the cohort of glioma patients." (PMID 34361055, 2021). "The Period2 (Per2) gene is an essential component of the mammalian circadian clock and is strongly linked to glioma occurrence and its response to radiotherapy." (PMID 27036047, 2016). "We previously reported that Per1 and Per2 expression abnormalities are associated with glioma occurrence." (PMID 27036047, 2016). "In our previous study, we reported that Per1 and Per2 expression abnormalities are associated with glioma occurrence." (PMID 27036047, 2016). "Our former study has showed that Per1 and Per2 expression abnormalities can be associated with the occurrence of glioma." (PMID 25760074, 2015). "Similarly, the downregulation of Per2 was observed in samples derived from The Cancer Genome Atlas (TCGA) database, and Per2 deregulation in tumors was found to be linked with increased mortality in the cohort of patients with glioma." (PMID 40495887, 2025). "In more detail, radioresistance was increased when PER2 was ablated either in a loss-of-function mouse model or an orthotopic mouse model using U343 PER2 KD cells, and radioresistance was highest at the timepoint of the PER2 trough in a rat glioma model." (PMID 38378853, 2024). "Furthermore, abnormalities in expression of PER1 and PER2 are associated with the occurrence of glioma." (PMID 32195174, 2020). "Abnormalities in Per1 and Per2 expression are associated with the occurrence of gliomas." (PMID 28620312, 2017). "Per2 has been linked to DNA damage response pathways, and low Per2 expression may increase the efficacy of radiotherapy against glioma by promoting apoptosis." (PMID 27036047, 2016). "In addition, high expression of Per1 and Per2 in glioma tissue was associated with increased sensitivity to x-irradiation." (PMID 25760074, 2015). "This suggests that the low proliferation and high apoptosis associated with low Per1 expression in glioma may result from the coincidence at ZT12 of high Per2 expression and low Per1 expression." (PMID 25760074, 2015). "It has also been observed that there is a lower level of Per2 expression in non-glioma cells, which indicates the differences in CCG expressions between malignant and normal brain tissues." (PMID 40495887, 2025). "PER2 expression increased significantly, which confirmed that metformin can regulate the expression of certain biological rhythm genes in glioma cells." (PMID 40166471, 2025). "A disrupted level of Per2 expression has been observed in gliomas as compared to normal brain tissues." (PMID 40495887, 2025).
glioma (continued). "Using Per2-fusion luciferase-expressing C6 rat glioma cells (Per2::luc C6 cells), we synchronized cell clock genes with dexamethasone, added PTGFR agonists at different times, and tested their effects on the periodicity of Per2::luc activity." (PMID 38339119, 2024). "Since Period genes are downregulated in glioma samples compared to normal brains, we evaluated how the disruption of Per2 affects cell cycle progression." (PMID 38907776, 2024). "It is noteworthy that the expression of PER1, PER2, PER3 is also downregulated in high-grade gliomas and associated with increased proliferation and survival of glioma cells." (PMID 36796229, 2023). "This study confirmed that LbGP can inhibit the proliferation of glioma cells and that LbGP upregulates the expression of PER2 in the PKA-CREB pathway." (PMID 37069338, 2023). "The databases were next used to examine the correlations between mRNA levels of Per2 and Id3, which revealed that they were inversely correlated in human glioma." (PMID 35599595, 2022). "Based on these findings, we conjecture that Per2 regulates glioma through downstream Id3, and in this study, protein levels of Id3 were reduced when Per2 was overexpressed, while Id3 overexpression did not change the levels of Per2 protein." (PMID 35599595, 2022). "Per2 was stably overexpressed (Per2 OE) in U87 and U251 cells using lentiviral vector transfection to assess the functional consequences of increasing levels of Per2 in glioma, while empty lentiviral vector-transfected cells served as controls." (PMID 35599595, 2022). "Multiple studies have found that Per2 appears to primarily mediate antitumorigenic programs, especially in gliomas." (PMID 35599595, 2022). "Our previous studies further reinforced that in glioma and glioma stem cells (GSCs), Per2 plays a vital role in the biological mechanism of malignant progression." (PMID 35599595, 2022). "By using a wide range of functional examples, overexpression of Per2 restrains malignant biological behaviors in glioma cells by many ways, while Id3 promotes malignant biological behaviors in glioma cells." (PMID 35599595, 2022). "We investigated the downstream processes of Per2 and discovered that Per2, a tumor suppressor gene, inhibited glioma cell proliferation by downregulating Id3 expression in glioma." (PMID 35599595, 2022). "Next, CCK8, colony formation, Transwell, wound healing assay, flow cytometry and xenografts in mice were used to acknowledge the effect of Per2 and Id3 in glioma." (PMID 35599595, 2022). "In this study, we analyzed the clinical significance and relevance of Per2 and Id3 in patients with glioma using bioinformatics combined with immunohistochemistry of clinical samples." (PMID 35599595, 2022). "In summary, Per2 OE restrains proliferation, migration, invasion, and cell cycle progression, indicating the tumor suppressor role of Per2 in glioma cells." (PMID 35599595, 2022). "CCK-8 assay, colony formation assay, Transwell assay, the wound healing assay, flow cytometric, and Xenograft nude mice were used to acknowledge the impact of Per2 and Id3 on biological behavior of glioma." (PMID 35599595, 2022). "In this study, we employed multiple laboratory techniques to acknowledge the biological activities and processes of Per2 and Id3 in glioma." (PMID 35599595, 2022). "We discovered that Id3 OE caused glioma cells to proliferate faster than controls in CCK-8 assays and colony formation, while proliferation was inhibited when the transfected Per2 OE vector was present." (PMID 35599595, 2022). "Previous research indicated that Per2 is highly expressed in low-grade glioma and exhibits low expression in high-grade glioma in clinical samples." (PMID 35599595, 2022).